LINC00905 (long independently transcribed non-coding RNA 905)
Synonyms: FLJ25328; LINC01855
Gene: Long non-coding RNA gene on chromosome 19 (16,031,170 to 16,066,312, forward strand). Ensembl gene ENSG00000167459.
Diseases named in the same sentence as LINC00905 in open-access papers:
LINC00905 is named in the same sentence as 2 diseases in open-access papers, as found by Europe PMC text mining. Sharing a sentence is not in itself a finding about the gene and the disease. The quoted sentences say what the papers report.
asthenozoospermia (1 paper, 2022). "Finally, LINC00905 is overexpressed in the testis and was found to be downregulated in patients with NOA, as well as differentially expressed in oligozoospermia and asthenozoospermia." (PMID 36290414, 2022).
LINC00905 also shares sentences with these, for which no sentence is quoted: male infertility (1 paper).